KRAS (KRas proto-oncogene, GTPase)
Diseases named in the same sentence as KRAS in open-access papers (continued):
Sharing a sentence is not in itself a finding about the gene and the disease.
cancer (continued). "KRAS mutations have been seen at the time of primary and acquired resistance to anti-HER2 therapy in other cancer types, including colorectal and gastroesophageal cancer; however, the impact of KRAS mutations co-occurring with potentially targetable alterations in PDAC has not been defined." (PMID 38406801, 2024). "We show that there is significantly more downregulation of autophagy in KRAS mutant CRC cells compared to KRAS wildtype cells, both at transcriptional and translational levels, suggesting that the KRAS mutation is advantageous for cancer growth, even in the presence of erlotinib." (PMID 39057088, 2024). "We have discovered that there are significant differences between the isoform interactions with the different mutants, which could be utilized in inhibitory treatments of mutated KRAS in different cancers." (PMID 39184150, 2024). "Mutations in KRAS have been associated with various cancers, including NSCLC." (PMID 38981473, 2024). "However, unlike the treatments targeting other gene alterations, such as EGFR mutations in NSCLC, targeting KRAS has yet to be successful enough to revolutionize KRAS-mutated cancer treatment." (PMID 38756650, 2024). "Based on the roles of conformational dynamics for SW1 and SW2, clarifying the molecular mechanism of the alterations in conformational behavior of KRAS caused by mutations and residue modifications remains a significant and outstanding aim because of its involvement in a variety of cancers." (PMID 38792177, 2024). "Oncogenic mutations in KRAS are among the most common in cancer." (PMID 38573819, 2024). "KRAS mutations occur in 11.6% of all cancer types, as per TCGA data." (PMID 39635441, 2024). "The highly mutated oncogene KRAS is one of thebest-established cancer targets." (PMID 38758695, 2024). "Mutations in KRAS are associated with different types of cancer." (PMID 38473821, 2024). "Currently, specific therapy is available only for certain cancers with the KRAS G12C mutation." (PMID 39596194, 2024). "Although oncogenic HRAS and KRAS mutations are most frequently found in epithelial cell-derived adenocarcinomas, their impacts have been discussed primarily on the basis of the fibroblast phenotype in the field of aging and cancer biology." (PMID 39456601, 2024). "Sotorasib was the first FDA-approved drug targeting KRAS mutations (G12C) in cancer." (PMID 38407980, 2024). "Mutations in KRAS disrupt its normal function, resulting in the constitutive activation of the protein, which is linked to an increased tumorigenicity, and it is associated with unfavorable prognosis in several cancers." (PMID 39457457, 2024). "Similarly, KRAS mutations have been frequently reported in several cancer types and have been linked to poor prognoses." (PMID 39685930, 2024). "Furthermore, the distribution of somatic mutations is a contributing factor to disparities in cancer health outcomes, especially in the only currently clinically targetable KRAS G12C allele." (PMID 38668053, 2024). "KRAS is a prominent proto-oncogene, mutated in nearly 40% of cancer cases." (PMID 39354505, 2024).
cancer (continued). "Our results indicate that fibroblasts might be aiding the metabolic needs of cancer cells by providing them with substrates and signaling molecules, which can help them overcome the metabolic stress caused by KRAS inhibition." (PMID 39061234, 2024). "The co-occurrence of KRAS and other driver mutations could be detrimental or beneficial, which needs a better screening strategy to understand the pathology of cancer." (PMID 39056802, 2024). "Thus, high pCASTOR1 scores in the early-stage male patients with KRAS mutations conferred adverse disease outcomes with prognosis similar to those in the advanced stage cancer." (PMID 39385301, 2024). "KRAS is one of the frequent driver mutations in several human cancers." (PMID 39056802, 2024). "KRAS mutation also influences or impacts other factors in cancer pathology." (PMID 39056802, 2024). "The study also confirmed that processed KRAS peptides were effectively presented to T cells, supporting the idea that KRAS mutations could be good targets for cancer treatment." (PMID 38732150, 2024). "ELI-002 is composed of a lipid-conjugated immune-stimulatory oligonucleotide (Amph-CpG-7909) and a combination of lipid-conjugated peptide-based antigens (Amph-Peptides) designated by “NP” to target a broad spectrum of KRAS mutations expressed in various cancers." (PMID 39335494, 2024). "KRAS mutations are among the most common genetic alterations in cancer." (PMID 38607003, 2024). "Combining with other keywords active at that time, the preliminary research concentrated on clinical trials and efficacy using drugs like gefitinib, cetuximab plus irinotecan, and erlotinib that target the KRAS upstream gene EGFR in cancer patients with KRAS mutations." (PMID 38706597, 2024). "The cancer cells carrying KRAS mutations can be divided into two categories, KRAS-dependent and KRAS-independent, the latter of which may be less sensitive to KRAS inhibitors." (PMID 38763973, 2024). "It is estimated that around 25% of all cancer cases involve, at least in part, a KRAS mutation." (PMID 38397135, 2024). "In one study, the most aggressive behavior was found for cancers with KRAS mutations." (PMID 38392199, 2024). "Recent research has demonstrated that the presence of the KRAS mutation may directly influence medical decisions in patients with cancer." (PMID 38666907, 2024). "KRAS is frequently mutated in various cancers and is emerging as a target for cancer therapy." (PMID 39594178, 2024). "KRAS mutation, a common phenomenon in cancer, is found in ~40% of CRCs." (PMID 38407980, 2024). "KRAS mutations are found in various types of cancer, but their frequency is diverse." (PMID 39457426, 2024). "KRAS mutations are the most common cancer driver events in both White and Black Americans." (PMID 39436906, 2024). "KRAS is most frequently mutated across all cancers, and there is a vast spectrum of over 200 amino acid substitutions that can occur between all three Ras isoforms, of which G12V and G12D are the most frequent mutations, comprising 45% of all amino acid substitutions in Ras." (PMID 39372214, 2024).
cancer (continued). "These small molecules glue together the GAP and the mutated KRAS molecules and may serve as new cancer drugs for the most lethal, most difficult-to-treat, carcinomas." (PMID 38473821, 2024). "Mutation in the KRAS gene is one of the most common oncogenes in many types of cancer." (PMID 39184150, 2024). "However, genetic polymorphisms play an important role in increasing the risk of various diseases, including types of cancers, especially some SNPs of KRAS and NRAS genes, which are associated with a higher risk of LSCC." (PMID 39867023, 2024). "In certain instances, HPV infections may influence cell behavior and potentially interact with other genetic factors, such as KRAS mutations, possibly promoting cancer development." (PMID 39673361, 2024). "Mutation in the KRAS gene is also responsible for the formation of cancer." (PMID 38794122, 2024). "Although there is no publicly available preclinical evidence, it might be extrapolated from this finding that KRAS G12C inhibitors may sensitize KRAS G12C-mutated cancers to PARP inhibitors by suppressing the RAS/MAPK pathway and increasing FOXO3a expression." (PMID 38756650, 2024). "The use of a newly deployed assay for probing KRAS mutation status was instrumental for identifying hybrid ductal epithelial cell, which uniquely shared transcriptional elements with normal ductal and cancer cells." (PMID 39485038, 2024). "It was reported that glutaminolysis is caused by the activation of KRAS in various cancers." (PMID 38809881, 2024). "Moreover, adagrasib (MRTX849) is a specifically optimized oral inhibitor of KRAS G12C mutant by irreversibly and selectively binding to KRAS G12C in the inactive state, preventing it from sending cell growth signals and causing cancer cell death." (PMID 39308869, 2024). "The KRAS gene is one of the most frequently mutated oncogenes in human cancers, with mutations commonly identified in approximately 90%–95% of pancreatic ductal adenocarcinoma (PDAC), 40% of colorectal cancers (CRC), and 25%–30% of non-small cell lung cancers (NSCLC)." (PMID 39850800, 2024). "Importantly, intratumoral microbiome communities can also be associated with the mutational landscape of the cancer cells, like the associations established between Bacteroides and KRAS mutations or Proteobacteria and microsatellite instability in CRC tissues." (PMID 39120310, 2024). "Notably, the frequency of KRAS mutations increased from benign to borderline to malignant stages, underscoring its importance in the continuum of cancer developmen." (PMID 39040449, 2024). "The role of KRAS, when activated through canonical mutations, has been well established in cancer." (PMID 38637419, 2024). "CRAs harboring both APC and KRAS mutations may demonstrate a heightened predisposition toward carcinoma development." (PMID 39554798, 2024). "Nanomedicine offers promising opportunities for improving KRAS-mutated cancer therapy, but there are still several limitations and challenges that must be overcome related to toxicity, targeted delivery, stability, manufacturing and scale-up, and regulatory approval." (PMID 37376135, 2023). "We aimed to characterize the heterogeneity of genetic variations accompanying low-frequency KRAS mutation detected in plasma ctDNA of these patients, and to evaluate the potential prognostic values of low-frequency ctDNA KRAS mutation in cancer progression and treatment responses." (PMID 37511664, 2023). "In addition, CTLA-4 gene expression level tended to be higher in CTCs and PBMCs in patients with KRAS mutation than in patients with KRAS wild type (data obtained from Gold Coast University Hospital and detected by next-generation sequencing on cancer tissue)." (PMID 36902476, 2023). "Furthermore, BRG1 effects cancer proliferation in oncogenic KRAS mutated cancers, with varying directionality." (PMID 36769189, 2023). "KRAS mutations occur in nearly 30% of human cancers, among which about 14.5% are G12C mutations." (PMID 38104151, 2023).
cancer (continued). "However, other studies have concluded that MAPK pathway inhibition in KRAS-mutated cancers triggers a resistance mechanism through the induction of protective autophagy." (PMID 37996408, 2023). "Indeed, our results provide evidence that cancer develops only in mice having a high level of KRAS oncogene mutation paralleled by a massive let-7a downregulation." (PMID 37511536, 2023). "This search for KRAS mutations in cytological material has been validated by numerous prospective studies, including notes in two indications: the differential diagnosis between pseudotumor CP and cancer developed on CP and in the diagnosis of cancer." (PMID 36765725, 2023). "By disrupting the oncogenic alleles, cancer cell growth was inhibited, indicating that KRAS mutant-specific CRISPR/Cas9-mediated genome editing could potentially be adopted for cancer therapy." (PMID 37669923, 2023). "Moreover, the most prevalent of non-G12C KRAS mutants found in cancer are thought to be deficient in GAP-assisted GTP hydrolysis and exist in a non-excitable or constitutively active state." (PMID 37258666, 2023). "The mutational mosaic of KRAS is distinguishable among different cancer types." (PMID 36808143, 2023). "Rason KO markedly inhibited lung tumor formation in KP mice, as monitored by micro-CT measurement of lung tumor incidence and size, and significantly prolonged mouse survival, suggesting a common mechanism underlying the protumor function of RASON in KRAS mutant cancers." (PMID 36241718, 2023). "KRAS mutations have long been considered attractive targets for cancer therapy." (PMID 37662925, 2023). "One important combination is with direct KRAS inhibitors such as in G12C-mutated cancers." (PMID 37569406, 2023). "Notably, PDAC with mutated KRAS has a loss of miR-145 expression, leading to an increase in the expression of pluripotency markers in cancer stem cells." (PMID 37239940, 2023). "Research suggests that co-treatment using KRAS G12C inhibitors and IN10018 is likely to benefit cancer patients with mutated KRAS G12C and may also prevent resistance to KRAS G12C inhibition by targeting dysregulated FAK-YAP signaling and fibrogenesis." (PMID 37749625, 2023). "Indeed, with the view of the ongoing effort to develop drugs that can efficiently target KRAS mutated cancer cells, there are many recent reports that successfully leveraged the ferroptosis machinery to promote cell death in KRAS-driven tumors." (PMID 36675307, 2023). "Targeting KRAS mutations is regarded as the “holy grail” of targeted cancer therapies." (PMID 37110848, 2023). "Determining which of these inhibitors is most effective for patients with NSCLC and other cancers with KRAS G12C mutations, and whether combining these inhibitors with other drugs leads to better treatment outcomes, are key emerging questions." (PMID 36674513, 2023). "In contrast to aNSCLC patients with EGFR or ALK driver mutations, patients with KRAS G12C–positive cancer may benefit from CIT monotherapy." (PMID 37069542, 2023). "This is in line with our results and confirms in vivo the radio-sensitizing effect of a potent KRAS inhibitor in preclinical setting, and therefore the interest to move towards the implementation of combinatorial strategies involving RT and KRAS inhibitors in KRAS-mutated cancers." (PMID 37907934, 2023). "Furthermore, higher dosage of the mutant allele of KRAS than its WT counterpart has been associated with poor prognosis in cancer patients." (PMID 37298264, 2023).
cancer (continued). "We hypothesize that the link between KRAS mutation and the increased risk of thrombosis is related to the underlying mechanisms of cancer-associated thrombosis." (PMID 38069251, 2023). "Different fromTP53, KRAS is one of the most commonly mutated driver genes in human cancers with the highest mutation rate (over 95%) in pancreatic ductal adenocarcinoma (PDAC), which is an extremely lethal cancer type with no effective cure currently available." (PMID 37337636, 2023). "FSP1 (AIFM2) upregulation in KRAS-mutant cancer cells has been linked to ferroptosis resistance." (PMID 37371948, 2023). "There are also some pan-cancer studies focusing on the oncogenic mechanism of KRAS mutations." (PMID 36675641, 2023). "Furthermore, in line with our unpublished findings and others, KRAS mutant cancer is more susceptible to autophagic inhibition in the context of lung cancer, particularly in a nutrient-deprived microenvironment." (PMID 37363731, 2023). "Moreover, despite the recent approval, the development of resistance to the KRAS G12C inhibitors has already been reported, limiting the therapeutic efficacy and clinical application of such drugs to treat KRAS-mutated cancers." (PMID 37376135, 2023). "The presence of KRAS mutations is important for cancer diagnosis and treatment." (PMID 37764496, 2023). "KRAS exhibits the highest mutation frequency in cancer, present in ~85% of cases." (PMID 37892237, 2023). "Efficacy of clinical trials adapted to cancers with mutated KRAS in last 5 years." (PMID 37250144, 2023). "Ongoing clinical trials for cancers with KRAS mutations (except for G12C)." (PMID 37250144, 2023). "Furthermore, KRAS mutations stimulate scavenger pathways, such as macropinocytosis and autophagy, to sustain cancer cell survival under nutrient deprivation." (PMID 36674902, 2023). "Furthermore, the KRAS mutation stands out as the most extensively recognized oncogene, displaying the highest frequency of mutations across diverse cancer types." (PMID 37933355, 2023). "Hence, we sought to gain insights into the functional significance of KRAS mutation in cancer immunotherapies, including anti‐PD‐1 and adoptive T cell therapies." (PMID 36599679, 2023). "This may also explain why KRAS oncogenic mutants may be causing cancer only in specific tissues despite KRAS being expressed in most cells and tissues." (PMID 36894174, 2023). "Since cell-surface expression of CD47 is a major mechanism used by cancer cells to evade macrophage phagocytosis, we investigated whether the KRAS mutation status could affect CD47 expression in lung tumors." (PMID 36413402, 2023). "Mutations in KRAS, different mutant subtypes of KRAS, and other genetic co-alterations with the KRAS mutation may all have an impact on the clinicopathological features and prognoses of cancer patients." (PMID 36675641, 2023). "Oncogene KRAS activation by endogenous mutations or exogenous expression in luminal epithelial breast cells also promotes development of neoplastic lesions that evolve to claudin-low or basal-like cancers with triple-negative phenotypes, in a mouse model." (PMID 37345027, 2023). "Thus, KRAS-mutated cancers are actively signaling, resulting in uncontrolled cellular proliferation that eventually leads to carcinogenesis." (PMID 36831298, 2023). "Interestingly, 2D and 3D cell studies revealed their ability to induce cancer cell death at low micromolar doses, being extremely effective against human pancreatic KRAS mutated cancer cells." (PMID 36835086, 2023). "(Menispermaceae) with anticancer potential in some cancers with KRAS mutations." (PMID 37174108, 2023). "Further BRG1/KRAS interaction in other cancers may support a greater understanding of how to properly treat KRAS mutated cancers." (PMID 36769189, 2023). "Despite their similarity, KRAS is far more frequently mutated in cancer." (PMID 36864243, 2023).